INKA1 (inka box actin regulator 1)
Description:
Inhibitor of the serine/threonine-protein kinase PAK4. Acts by binding PAK4 in a substrate-like manner, inhibiting the protein kinase activity.
Synonyms: Inca; C3orf54; FAM212A
Gene: Protein-coding gene on chromosome 3 (49,803,240 to 49,805,030, forward strand). Ensembl gene ENSG00000185614.
Subcellular location: Nucleus; Cytoplasm
Subcellular location (Human Protein Atlas): Nucleoplasm; Vesicles
Genetic constraint (gnomAD): Loss-of-function variants: 14 observed, 20.89 expected, observed/expected ratio (o/e) 0.67, 90% interval 0.44 to 1.05. The upper end of that interval is the gene's LOEUF score, 1.05, which puts it in group 4 of 6, group 1 being the genes least tolerant of losing a copy. Missense variants: 353 observed, 386.7 expected, observed/expected ratio (o/e) 0.91, 90% interval 0.84 to 1. Synonymous variants: 133 observed, 147.84 expected, observed/expected ratio (o/e) 0.9, 90% interval 0.78 to 1.04.
Homologues: Orthologues: chimpanzee INKA1 (99% identical), macaque INKA1 (96% identical), rabbit INKA1 (84% identical), dog INKA1 (82% identical), rat Inka1 (80% identical), guinea pig INKA1 (80% identical), mouse Inka1 (80% identical), pig INKA1 (74% identical), zebrafish inka1a (36% identical), zebrafish inka1b (35% identical), tropical clawed frog inka1 (34% identical). Paralogues in human: INKA2 (21% identical).
Diseases named in the same sentence as INKA1 in open-access papers:
INKA1 is named in the same sentence as 3 diseases in open-access papers, as found by Europe PMC text mining. Sharing a sentence is not in itself a finding about the gene and the disease.
INKA1 shares sentences with these, for which no sentence is quoted: brain disorder (1 paper); cleft lip (1); insomnia (1).